S100A6 (S100 calcium binding protein A6)
Diseases named in the same sentence as S100A6 in open-access papers (continued):
Sharing a sentence is not in itself a finding about the gene and the disease.
tumor (continued). "To confirm the recently suggested overexpression of S100A6 mRNA in tumor samples of patients with intrahepatic CCA, we analyzed tumor S100A6 mRNA levels in a cohort of patients with histologically confirmed CCA (n = 8) by using qPCR and compared them to healthy controls (n = 4)." (PMID 27709523, 2016). "Although S100A6 was expressed at significantly higher levels in human and murine CCA tumor samples, S100A6 serum levels were not regulated in patients with CCA and are thus not suitable for diagnosis of CCA." (PMID 27709523, 2016). "In the present study, we demonstrate that S100A6 expression levels are significantly up-regulated in CCA tumor tissue but measurements of circulating S100A6 are not suitable for the diagnosis of CCA." (PMID 27709523, 2016). "High expression of annexin II correlated with age, location of tumor, size of tumor, differentiation, histological type, depth of invasion, vessel invasion, lymph node metastasis, distant metastasis and Tumor, Node, Metastasis (TNM) stage, and also with expression of S100A6." (PMID 22681645, 2012). "S100A6 immunolabeling was observed in tumor tissue but not in surrounding mesentery or abdominal organs (intestines, liver, kidney, urinary bladder, spleen, pancreas, uterus, and ovary)." (PMID 19888321, 2009). "Interestingly, the immunoreactivity of the tumor cell complexes was stronger at the tumor margin than that in the central tumor area in CRC, when we used the specific antibody directed against S100A6." (PMID 19048101, 2008). "Furthermore, we also concluded that down-regulated of S100A6 (F = 3.52, P=0.0164), S100A10 (F = 5.36, P=0.0015), S100A16 (F = 6.69, P=0.00027), and SDC1 (F = 4.02, P=0.00849) were effectively related to lower tumor stage." (PMID 35342420, 2022). "Moreover, upregulation of genes CLU, NNMT, and S100A6, which are known to promote RCC cell proliferation and metastasis, were found exclusively in the tumor compartment of Endo-2 and could indicate a supportive role of these cells to RCC progression." (PMID 36180422, 2022). "Based on the gene markers and the high expression of HLA-DPB1, S100A6, HLA-DRA, and other genes related to antigen presentation in GSVA, SC-C1 and SC-C3 cells were mainly enriched in hematopoiesis, suggesting that SC-C3 cells may be related to tumor vascular proliferation." (PMID 36304995, 2022). "Furthermore, the tumor stages had no influence on S100A6 serum levels." (PMID 27709523, 2016). "Finally, pre-operative serum levels of S100A6 were not altered in patients with incomplete tumor resection (R1), compared to patients with complete resection (R0) and did not correlate with clinical symptoms of CCA such as fatigue, pain or impaired ECOG performance status." (PMID 27709523, 2016). "Moreover, our observation that high levels of S100A6 correlated with the expression of membranous annexin 2 in patient tumours whilst low S100A6 levels correlated with a lack of membranous annexin 2 suggests that S100A6 may affect the localisation of annexin 2 to membranes." (PMID 19724273, 2009).
cancer (90 papers, 2000 to 2025). A tumor composed of atypical neoplastic, often pleomorphic cells that invade other tissues. "Meanwhile, it became clear that S100A6 expression was altered in various pathological states and correlated with the stage/progression of many diseases, including cancers, indicative of its important, and possibly causative, role in some of these diseases." (PMID 36674873, 2023). "S100A6 expression has been associated with worse prognosis or the progression of several cancers including oncogynecology, colorectal, gastric, and renal." (PMID 32344524, 2020). "S100A6 was pursued for initial validation as a candidate serum biomarker due to its association with cancer progression." (PMID 19888321, 2009). "The human S100A6 gene is located on chromosome 1q21, and the protein product has been implicated in growth and differentiation as well as in a variety of human cancers." (PMID 15280928, 2004). "S100A6 is an important calcium signal-regulating gene, and the calcium-binding protein it encodes is a member of the S100 family, which is associated with DNA damage and a variety of cancers." (PMID 36232318, 2022). "Overexpression of S100A6 is associated with poor prognosis of patients in many cancer types." (PMID 30440021, 2018). "A large number of studies have associated S100A6 with the development of cancer." (PMID 27709523, 2016). "Given the results of previous studies showing S100A6 expression to be increased in all cancers as well as the correlation between expression and malignant transformation and invasion, our finding of loss of S100A6 expression in all adenocarcinomas studied was unexpected." (PMID 15280928, 2004). "In addition, due to changes in S100A6 expression during cancer progression, the protein has been recognized as a useful diagnostic and prognostic tool for defining cancer stage and patient prognosis as, for example, in the case of pancreatic and lung adenocarcinoma." (PMID 36674873, 2023). "Through correlation analysis, we observed that LAD1 expression levels were statistically associated with several cancer-related genes, including SFTPB, S100A6, CEACAM6, KRT19, S100A10, ANXA2, S100A11, and CAPN2." (PMID 41423496, 2025). "Our results are consistent with previous findings, showing that S100A6 is overexpressed post‐IR in other cancer cells." (PMID 39375892, 2025). "Comparing the mRNA expression levels of top 8 DEGs in tissue samples, IGHG1 and S100A6 were found at higher expression levels in cancer tissues (P < 0.001)." (PMID 38898490, 2024). "The two S100 genes S100A4 and S100A6, which are involved in many cellular processes including inflammation and cancer progression, were also highly expressed in the malignant T cells." (PMID 39169943, 2024). "All these data, together with the fact that S100A6 is detected in cancer stem cells, point to a potential role of S100A6 in the development of malignancy." (PMID 36674873, 2023). "Immunohistochemistry, RT-PCR, and scRNA-seq techniques revealed the expression of S100A6 in epidermal, neural, cancer, hematopoietic, and epithelial stem cells." (PMID 37670392, 2023). "Based on these data, it has been proposed that the serum level of S100A6 can be used as a biomarker in detecting these types of cancer and serve as an indicator of their progress." (PMID 36674873, 2023). "In previous studies of cancer cells, the effect of S100A6 on motility either facilitated or inhibited cellular migration." (PMID 36748983, 2023). "The results exhibited that the sensitivity of cancer cells to paclitaxel-induced cytotoxicity, apoptosis, and cell-cycle arrest was enhanced obviously by S100A6, which is similar to the growth inhibitory activity." (PMID 37217945, 2023).
cancer (continued). "Among non-cancer pathologies, a high S100A6 level is typical for fibrosis-related diseases, characterized by excessive deposition of extracellular matrix proteins by activated fibroblasts." (PMID 36674873, 2023). "GSEA revealed that S100A6 is involved in cancer-related pathways and glycometabolism-related pathways." (PMID 35432196, 2022). "Specifically, S100A6 promotes the proliferation and motility of cancer cells and induces the activation of fibroblasts." (PMID 36072587, 2022). "S100A6 has been proved to be highly expressed in epithelial cells, fibroblasts, and some cancer cell types, function of which was still unclear." (PMID 35342420, 2022). "A total of nine genes are located on 1q, of which S100A6 has been described in relation to 1q21 amplification in MM and other cancer types." (PMID 34448362, 2022). "In relationship to cancer, the S100A6 protein co-regulates the proliferation and apoptosis of cells." (PMID 33466593, 2021). "S100A6 protein (calcyclin), a small calcium-binding protein of the S100 family, isoften upregulated in various types of cancers, including hepatocellular carcinoma(HCC)." (PMID 33335992, 2020). "We propose essential roles of acid adaptation in cancer cells EMT process through S100 proteins such as S100A6 that can be used as therapeutic strategy targeting both acid-adapted and malignant phenotypes." (PMID 32211331, 2020). "S100a6, encoding S100 calcium binding protein A6, is associated with poor prognosis of DCIS patients and several cancer types overexpress this S100 gene, suggesting S100a6 plays an oncogenic role in tumorigenesis." (PMID 32785175, 2020). "S100A6 expression has been associated with protection from TNF-α-induced apoptosis in cardiomyocytes, decreased metastasis rate in cancer of the bone, as well as the regulation of cell cycle progression." (PMID 28206967, 2017). "S100A6 has been reported to be highly up-regulated in many cancers, we thus examined the expression in ccRCC tissues and cell lines by quantitative RT-PCR (qRT-PCR), western blotting assay, and immunohistochemical staining." (PMID 25760073, 2015). "Expression of S100A6 was further examined in human cancer cell lines and tissue derived from OVCA patients." (PMID 19888321, 2009). "Although S100A6 overexpression in pancreatic and other cancers, including gastric, thyroid, breast and colorectal has been documented, its precise role in cancer is not known." (PMID 19724273, 2009). "In conclusion, this study demonstrates the presence of S100A6 in OVCA cancer sera for the first time and further documents the potential use of S100A6 as an OVCA biomarker." (PMID 19888321, 2009). "Two members of the S100 gene family, S100A6 and S100A4 have been suggested to be associated with cancer invasion and metastasis." (PMID 10952782, 2000). "Importantly, high S100A6 expression showed a positive correlation with cancer recurrence in ESCC patients." (PMID 39375892, 2025). "S100A6 is also expressed in ovarian and other cancer tissues." (PMID 37670392, 2023). "With paclitaxel, S100A6 enhanced the sensitivity of cancer cells to paclitaxel-induced colony formation suppression, and suppression of colony formation in S100A6-transfected cells was more obvious than that in control-transfected cells after treatment with paclitaxel." (PMID 37217945, 2023). "An increased level of S100A6 has been observed in different pathologies, including cancers." (PMID 36674873, 2023). "Interestingly, the immortalized HPNE cells show higher levels of S100A6 transcript (Ct = 7.93 +/− 0.31) than any of the cancer cell lines." (PMID 37627239, 2023). "Elevated S100A6 levels were shown to induce cell proliferation and migration in cancer cells." (PMID 38203551, 2023).
cancer (continued). "In conclusion, S100A6 is differentially expressed in a variety of cancers, and detection of serum S100A6 levels may aid in cancer diagnosis." (PMID 34148033, 2021). "S100A6 is highly expressed in fibroblasts, epithelial cells, and different cancer cells." (PMID 34060533, 2021). "S100A6 is upregulated in the SW480 cancer cell line (p < 0.01)." (PMID 32422974, 2020). "S100A6, also called calcyclin, is reportedly involved in many aspects of cancers." (PMID 30440021, 2018). "Previous research reported that S100A6 could be used as a marker to further subdivide early-stage and late-stage cancer patients into different prognostic groups in GC." (PMID 28423550, 2017). "In particular, S100A4, S100A6, S100A7 and S100A10 have been found to be overexpressed in some cancer types, and could be associated with aggressive cancer phenotype." (PMID 27008379, 2016). "They investigated S100A6 in normal colon tissue and in colorectal adenomas and carcinomas." (PMID 26880885, 2016). "The interactions between annexin II and S100A6 may play an important role in cancer metastasis and may provide a novel therapeutic approach for treating a variety of cancers." (PMID 22681645, 2012). "The fact that S100A6 is elaborated by a number of human cancers, suggests that its use as a sole biomarker may encounter potential false positive incidences, akin to CA-125." (PMID 19888321, 2009). "Therefore, incorporating S100A6 into a panel of cancer biomarkers represents a logical approach to be pursued." (PMID 19888321, 2009). "There are conflicting reports about the role S100A6 plays in cancer." (PMID 19888321, 2009). "To determine whether the reductions in cancer motility after depletion of S100A6 expression might reflect losses in growth, we undertook measurements of proliferation of cells 72 h after transfection with control- and S100A6-targeting siRNAs." (PMID 19724273, 2009). "In order to indicated the role of the family members in HCC development, we further analyzed the expression of S100A4, S100A6, S100A10, S100A11 and S100A16 in pan-cancer, and the results suggested that they were highly expressed in most tumors." (PMID 37420211, 2023). "DNA hypomethylation also contributes to the regulation of the expression of S100A6, S100A8 and S100A11 in various cancers." (PMID 33466593, 2021). "The data showed that S100A4, S100A14 and S100A16 were significantly higher in PDAC tissues compared with their counterparts, but the protein level of S100A2, S100A6 and S100A10 were similar between cancer tissues and their counterparts." (PMID 34530774, 2021). "Malignant tumors are characterized by high expression levels of S100A6 and ANXA11, suggesting that these proteins are related to cancer biology and regulation of the cell cycle." (PMID 32824294, 2020). "For example, the over-expression of S100A2, S100A3, S100A6, S100A8/A9, S100A11 and S100A14 have been documented in several cancer types." (PMID 30018736, 2018). "For example, over-expression of S100A2, S100A3, S100A6, S100A8/A9, and S100A11 is related to several types of cancer, whereas other types of cancer are characterized by the under-expression of these same proteins." (PMID 25988147, 2014). "For example, S100A4, S100A6, S100A7 and S100B play oncogenic roles in cancer development, whereasS100B, S100A2, and S100A11 are believed as TSGs." (PMID 23894350, 2013). "The identification of many well-defined cancer gene markers (representing oncogenes), such as EGFR, osteopontin (SPP1), ERBB3, MALAT1, S100A2, S100A6, ABCC3 and ELN3, as highly discriminative genes by the ECD is quite encouraging." (PMID 22369099, 2011). "Without paclitaxel, S100A6 suppressed the clonogenicity of cancer cells, and colony formation was suppressed in S100A6-transfected cells compared with control-transfected cells." (PMID 37217945, 2023). "S100A6 and murine double minute 2 (MDM2) are important cancer-related molecules." (PMID 37217945, 2023).
cancer (continued). "To identify factors potentially regulating serum S100A6 serum concentrations, we next analyzed correlations between S100A6 and routinely used laboratory markers in patients with cancer, but also this analysis revealed no clear correlation." (PMID 27709523, 2016). "S100A6 is expressed in ovarian and other cancer tissues, but has not been documented previously in ovarian cancer disease sera." (PMID 19888321, 2009). "In paired cancerous and matched normal ovary lysates from 2 patients, S100A6 was elevated in carcinoma tissue compared to its matched non-neoplastic ovarian tissues." (PMID 19888321, 2009). "Doing a differential expression between the two clusters of cancer fibroblasts, we found metastatic fibroblasts were found to express higher levels of soluble factors compared to primary fibroblasts including, CXCL12, S100A6, S100A10, SFRP2,SFRP4,IGF1, CXCL14, ANGPTL4 and IL6." (PMID 30383866, 2018). "However, the expression and role of S100A6 in cancer cells have not been extensively studied." (PMID 37217945, 2023). "S100A6 can promote the recruitment of neutrophils to PMN by increasing the permeability of ECs and stimulating neutrophil movement, and with increased penetration of N2-type neutrophils, more circulating cancer cells might survive due to the immunosuppressive microenvironment." (PMID 36612175, 2022). "Although for most S100s, and for HMGB1, the transcript levels were lower in the control HPNE cells than in the cancer cell lines, this was not the case for S100A4, S100A6, S100A7, S100A12, and S100A13." (PMID 37627239, 2023). "Based on the Oncomine database, there are no obvious distinctions in S100A1, S100A4, S100A5, S100A6, and S100A13 expressions between cancer tissues and normal colon mucosa, and S100A7, S100A12, and S100Z are slightly overexpressed in CRC tissues." (PMID 33294444, 2020).
infection (11 papers, 2004 to 2025). The state of being infected such as from the introduction of a foreign agent such as serum, vaccine, antigenic substance or organism. "The differences between infection in S100A10 KO versus A2t KO cells could be explained by the fact that S100 family members S100A4, S100A6, and S100A11 are also able to complex with AnxA2 and are expressed in cervical epithelium." (PMID 30076379, 2018). "In addition, the type 1 IFN related genes (OAS1G, OAS2, OASL1, OASL2, S100A6, S100A8, S100A9, S100A11) that are necessary for activation of the inflammasome in Francisella novida-infected macrophages, were highly induced over the course of infection and peaked at 24 hpi." (PMID 21110886, 2010).
neurodegenerative disease (11 papers, 2017 to 2025). A disorder of the central nervous system characterized by gradual and progressive loss of neural tissue and neurologic function. "The CacyBP/SIP target S100A6 is widely present in the nervous system, and its up-regulation is associated with certain neurodegenerative diseases." (PMID 28068373, 2017). "S100a6, which is upregulated with Mt3, expressed a calcium- and zinc-binding protein that has been associated with misregulation of zinc levels in several neurodegenerative diseases." (PMID 28587098, 2017). "The latest research also showed that S100A6 is involved in the process of neurodegenerative diseases." (PMID 34530774, 2021). "Although the S100A6 protein is usually up-regulated in neurodegenerative diseases, we found that in some brain structures, a decrease in S100A6 occurred in response to stress." (PMID 28068373, 2017). "Increased S100A6 levels have also been reported in other neurodegenerative diseases such as AD and ALS." (PMID 28449707, 2017). "Of note, in ALS, a neurodegenerative disease already described in connection with S100A6, the up-regulation of CacyBP/SIP could be detected by Western blot and LC-MS/MS analysis." (PMID 32492924, 2020). "Interestingly, differences in the expression pattern of S100A6 were observed in some other neurodegenerative diseases." (PMID 32492924, 2020). "Thus, data presented in this review open the way to the potential application of S100A6 as a marker of various neurodegenerative diseases and as a potential drug target." (PMID 32492924, 2020). "In addition, the high level of S100A6 is assumed to play an important role in certain neurodegenerative diseases." (PMID 28068373, 2017). "In particular, SRC-1-KO mice express significantly lower S100A6 and S100A11, and both genes have been demonstrated neuroprotective effects in neurodegenerative diseases." (PMID 40882002, 2025). "Taking into account the presence of S100A6 and its two ligands, CacyBP/SIP and Sgt1, in the brain, in this review, we focus on the expression/localization of these proteins in various brain structures and on their possible involvement in neurodegenerative diseases." (PMID 32492924, 2020).